NPIPB7 (nuclear pore complex interacting protein family member B7)
Synonyms: NPIPL1; LOC440350; A-575C2.4; A-761H5.5
Tractability: Antibody: UniProt places it where antibodies can reach, with high confidence; UniProt predicts a signal peptide or a membrane-spanning region; its Gene Ontology location is reachable by antibodies, with medium confidence.
Gene: Protein-coding gene on chromosome 16 (28,456,322 to 28,472,336, reverse strand). Ensembl gene ENSG00000233232.
Subcellular location: Secreted
Subcellular location (Human Protein Atlas): Nucleoplasm; Predicted to be secreted
Gene Ontology:
Cellular component: extracellular region
Genetic constraint (gnomAD): Loss-of-function variants: 0 observed, 1.77 expected, observed/expected ratio (o/e) 0, 90% interval 0 to 1.45. That is too few expected variants to judge how well the gene tolerates losing a copy. Missense variants: 10 observed, 42.29 expected, observed/expected ratio (o/e) 0.24, 90% interval 0.14 to 0.4. Synonymous variants: 7 observed, 16.31 expected, observed/expected ratio (o/e) 0.43, 90% interval 0.24 to 0.81.
Homologues: Paralogues in human: NPIPB9 (96% identical), NPIPB8 (95% identical), NPIPB15 (95% identical), NPIPB6 (90% identical), NPIPB13 (71% identical), NPIPB5 (71% identical), NPIPB12 (71% identical), NPIPB11 (71% identical), NPIPB4 (71% identical), NPIPB2 (64% identical), NPIPA7 (55% identical), NPIPA8 (55% identical), and 7 more.
Diseases named in the same sentence as NPIPB7 in open-access papers:
NPIPB7 is named in the same sentence as 2 diseases in open-access papers, as found by Europe PMC text mining. Sharing a sentence is not in itself a finding about the gene and the disease.
NPIPB7 shares sentences with these, for which no sentence is quoted: Obesity (1 paper); pneumonia (1).